MYC (MYC proto-oncogene, bHLH transcription factor)
Diseases named in the same sentence as MYC in open-access papers (continued):
Sharing a sentence is not in itself a finding about the gene and the disease.
tumor (continued). "Sublethal concentrations of each inhibitor were determined, followed by a synthetic lethal screen in KRASG12V/MYC tumor cells using non-toxic pairwise combinations of different inhibitors." (PMID 40550880, 2025). "USP28 interacts with c‐MYC through FBW7α and stabilizes c‐MYC in human tumor cells." (PMID 40227962, 2025). "KLF4, SOX2, and NANOG had low expressions in tumor tissue compared with its adjacent non-malignant (NM) counterpart, while no significant changes were found for c-MYC and OCT4 gene expressions." (PMID 41463190, 2025). "Similarly, increased m6A modification on Wnt pathway effectors such as MYC and CCND1 strengthens β-catenin signaling and drives tumor stemness, thereby fostering resistance to therapy." (PMID 41357193, 2025). "In addition, tumor tissues were stained with H&E to observe tumor cell morphology, and immunohistochemistry (IHC) was performed to detect the expression level of p21, WWP2, CMTM6, the cell cycle promoter c-MYC, and the proliferation marker PCNA." (PMID 41387673, 2025). "In addition, western blot was performed on tumor mass extracted from a xenograft model using A549 cells expressing shRING1, and similar to the results at the cell level, a tendency for CIP2A and c‐MYC to increase due to RING1 KD was confirmed." (PMID 41362702, 2025). "Although MYC is not necessary for the proliferation of normal hepatocytes or the initiation of these tumors, it is needed to sustain maximal tumor growth rates." (PMID 41440033, 2025). "NOTCH signaling is more involved in tumor growth than survival, especially through MYC pathway activation, which favors a cytostatic as opposed to cytotoxic effect of NOTCH inhibition." (PMID 40025676, 2025). "These cells tested positive for CD10, CD79a, PAX-5, BCL-2, BCL-6 (10-20%), and c-MYC, but most tumor cells were negative for CD20 on immunohistochemistry." (PMID 41142614, 2025). "Importantly, we further highlighted the advances in therapeutic strategies, including inhibitors of KRAS and MYC and restoration of TSG function, despite which mechanisms of resistance and tumor heterogeneity pose daunting challenges." (PMID 40227591, 2025). "In contrast, let‐7 acts as a tumor suppressor and may counterbalance the effects of miR‐21 by inhibiting oncogenes such as RAS and MYC." (PMID 40567015, 2025). "With respect to our in vivo studies, 4-OHT-induced MYC expression alone was not sufficient to generate a tumor phenotype, and the existence of animal models capable of recapitulating the features observed in human SebCA patients is lacking." (PMID 40422212, 2025). "This high level of transcription driven by high deregulated MYC expression is likely to be stressful and, if not properly relieved, will have deleterious consequences for tumor cells that require rapid proliferation." (PMID 40488968, 2025). "Exploring the underlying mechanisms, lactylation modification may contribute to tumor progression by activating oncogenic signaling pathways, such as HIF-1α and MYC." (PMID 41458606, 2025). "This tumor was categorized by methylome analysis as ATRT, MYC-subtype, WHO grade 4." (PMID 40052132, 2025). "The role of MYC in regulating the immune microenvironment is also significant, and further research could explore the role of DLGAP5 in the tumor immune microenvironment 71-73." (PMID 39990228, 2025). "A biopsy of the retroperitoneal tumor showed proliferation of small, atypical lymphoid cells with high nuclear-to-cytoplasm ratio, positive for CD10, CD19, CD79a, BCL-2, BCL-6, and c-MYC by immunohistochemistry." (PMID 41142614, 2025).
tumor (continued). "Similarly, depletion of PAF1c, a cofactor of MYC that ensures the transcription of DNA repair genes and suppresses MHC class I genes, results in complete tumor eradication in a subset of PDAC‐bearing mice." (PMID 40488968, 2025). "A similarly interspersed spatial pattern of MYC and non-MYC subclones was present in MYC-amplified tumours, yet islands of segregated non-MYC subclones were also observed (inset)." (PMID 40335697, 2025). "One reason GBM tumor cells have heightened sensitivity to HHT may be due to its effect on the activity of short-lived proteins, including MYC and other key cell cycle (e.g., cyclins)." (PMID 40346033, 2025). "The MYC oncogene is frequently deregulated in both non-small-cell lung cancer (NSCLC) and small-cell lung cancer (SCLC), contributing to uncontrolled proliferation, metabolic plasticity and tumour immune evasion." (PMID 40869000, 2025). "Although establishing a direct link between EV-miRNAs and MM tumor niches in the BM is not possible, isomiRs in our classification signatures target MYC or BCL2 oncogenes driving myelomagenesis." (PMID 40961943, 2025). "Alternatively, direct inhibition of c-MYC, MTDH, or Twist1 expression could effectively block downstream signaling, thereby suppressing EMT and limiting tumor progression." (PMID 40521202, 2025). "To evaluate the stemness role in ITAC prognosis, we analyzed, for the first time, the expressions of the Yamanaka factors KLF4, c-MYC, SOX2, OCT4, and NANOG in a cohort of patients with ITAC and investigate their possible roles in influencing tumor properties and survival." (PMID 41463190, 2025). "Skin cells lacking B56α can possibly not adequately control c-MYC activity during oncogenic stress, thereby promoting tumor initiation." (PMID 41146310, 2025). "Normally, antizyme serves as an anti-tumor regulatory agent by facilitating ubiquitin-independent degradation of several growth-promoting proteins including ornithine decarboxylase (ODC), cyclin D1, SMAD1, MSP1, Aurora A kinase and MYC." (PMID 39962590, 2025). "In addition to tumorigenesis, MYC also facilitates serine/glycine biosynthesis, along with HIF-1α and ATF4, which can integrate the anaerobic glucose metabolic cycle in tumor cells." (PMID 37450923, 2024). "PC-002, a first-class deubiquitinase (DUB) inhibitor that induces MYC degradation, also referred to as Sepantronium bromide or YM155, potently blocks BIRC5 expression to specifically induce apoptosis in MYC-dependent tumor cells by targeting the degradation of MYC protein." (PMID 39075086, 2024). "Mechanistically, while MYC inhibition destroyed CSCs, it also augmented the ability of cisplatin to kill non-stem tumor cells in HNSCC by enhancing the DNA damage response, which activated antitumor immunity by recruiting CD8+ T cells through chemokines." (PMID 38169606, 2024). "ICC recommends that cases previously reported as TdT-positive BL should be separated from BL and diagnosed as B-ALL/LBL with MYC rearrangement rather than BL as these neoplasms show immunophenotypic and molecular features of precursors B-cells." (PMID 39684922, 2024). "Intriguingly, MYC overexpression does not affect the expression levels of Exocyst complex subunits based on previous transcriptomics studies of this tumor model." (PMID 39535785, 2024). "CDK8/19i suppressed tumor growth in NSG mice, with no detrimental effects on body weight, but MYC-CaP-CR tumor suppression was not as complete in NSG mice as in the immunocompetent FVB." (PMID 38546787, 2024).
tumor (continued). "In support of the later model, we and others have uncovered critical roles of MYC and MYCN in maintaining the genomic stability of tumour cells, e.g., by coordinating transcription with DNA replication and by enabling promoter-proximal double-strand break repair." (PMID 39177021, 2024). "Notably, ectopic expression of the WDR5-2A mutant partially rescued cell proliferation and the tumor-promoting effect owing to the retention of the WBM (WDR5-binding motif) site, which interacts with other oncoproteins such as MYC." (PMID 38744853, 2024). "Given MYC(N)-overexpressing tumor cells strictly rely on NUDT1 to sanitize oxidized nucleotides for viability, we postulated that NUDT1 expression and/or catalytic activity should be enforced to adapt to MYC(N)-driven metabolic reprogramming." (PMID 38493213, 2024). "Let-7 targets multiple oncogenes (RAS, c-MYC, HMGA2 to date) and the prominent mechanisms by which let-7 exerts a tumor suppressive role is by repressing the translation of the three RAS proteins (HRAS, NRAS, and KRAS) and c-MYC, a downstream effector of RAS-ERK signaling." (PMID 38637419, 2024). "Although overexpression of MYC can also be seen in WNT-subgroup MB with no detrimental impact on survival, MYC-amplification has rarely been described in WNT-activated tumours." (PMID 38396397, 2024). "Trp starvation also resulted in lower MYC levels in xenotransplanted HUH7 cells but not in HCC53N, suggesting that Trp starvation limits tumor growth by mechanisms that do not require MYC repression." (PMID 38769298, 2024). "MYC amplification was further detected in circulation tumor DNA by next generation sequence in P2 and P8, without MYC or BCL-2 translocation." (PMID 38246951, 2024). "While numerous oncogenes have been identified as enhancers of tumor metastasis through the promotion of EMT, a subset of oncogenes, such as CREB1, MYC and FBXO22 (F-box protein 22), has been observed to concurrently facilitate proliferation while inhibiting EMT." (PMID 39883338, 2024). "Therapeutic targeting of MYC reduces CD47 and PD-L1, which results in tumor regression." (PMID 39201585, 2024). "MYC is involved in the recruitment of elements in TME, including making the stroma more suitable for tumor cell progression, facilitating immune evasion and promoting tumor to a more aggressive and metastatic phenotype." (PMID 39723215, 2024). "Its close proximity to MYC and its involvement in fundamental pathways such as MAPK signaling, NF-кB signaling, and the PI3K-Akt pathway have led to the identification of TRIB1 as an oncogene that plays a pivotal role in tumor progression and maintenance." (PMID 38791967, 2024). "Moreover, we report differences in oncogene expression such as MYC, MET and BRAF between ROS1+ tumor samples and cell lines, which should be taken into account when interpreting in vitro experiments." (PMID 39737401, 2024). "In B-lymphoma cells, the mutation or knockdown of KMT2D inhibited methylation of lysine 4 on histone H3 (H3K4), downregulated FBXW7 expression, activated NOTCH signaling pathway and downstream MYC/TGF-β1, resulting in alterations of tumor-induced regulatory T cell trafficking." (PMID 39113693, 2024). "While FOXO proteins may possess limited roles in promoting or delaying c-MYC–driven HCC formation, they might still function by modulating molecular features of the tumor cells." (PMID 39325536, 2024). "Combined targeting of EZH2, MYC and YAP/TAZ can, therefore, effectively de-repress expression of tumor suppressors and concurrently repress the expression of oncogenic pathways, to ultimately inhibit tumor growth." (PMID 39455556, 2024). "Significant tumor regression was detected in a mouse xenograft model treated with the PLK1 inhibitor, BI2536, compared with untreated controls, supporting a combined effect of PLK1 and MYC in tumorigenesis." (PMID 37450923, 2024). "We also observed significantly higher MYC expression in tumours with PMN-hit compared to those with no PMN-hit." (PMID 38877600, 2024).
tumor (continued). "The small tumors present in livers of the mice starved of Trp were positive for Ki67 and MYC, thus demonstrating a reduction in tumor burden, but not absence of tumors." (PMID 38769298, 2024). "Our study demonstrates that disrupting the KLF16/MYC loop with BET inhibitors, such as OTX015 or ABBV-744, in combination with chemotherapeutic agents like DDP or gemcitabine, significantly inhibits tumor growth and enhances the sensitivity of BLCA cells to chemotherapy." (PMID 39551759, 2024). "USP10, β-Catenin and the oncogene MYC were increased in tumour-samples compared to matched non-transformed tissue samples." (PMID 39443725, 2024). "Enrichment in MTORC1, MYC, and UPR in the GSEA results in the high SIGLEC9 expression tumor group may promote proliferation and adaptive survival mechanisms, creating an environment conducive to cytokine production, such as IL-10, SDF-1α, and IL-2." (PMID 39727942, 2024). "Enhanced glycolysis was the additional energy source for tumor proliferation and progression, for example, IGF2BP2 performed as a RBP and could regulate the m6A manner of MYC and thus promoted the aerobic glycolysis, migration and proliferation in CESC." (PMID 38383371, 2024). "In all tumor types, the expression of DKC1 was strongly correlated with MYC-TARGETS_V1 activation." (PMID 39162904, 2024). "Prior adult carcinoma trials have not shown consistent anti-tumor activity but were not designed for MYC-driven tumors or supported by activity in relevant preclinical models." (PMID 38200233, 2024). "Additionally, oncogenes such as MYC and N-MYC disrupt circadian rhythms by inducing REV-ERBα, which reduces BMAL1 levels and rhythmic activity, thereby impacting tumour growth and metabolism." (PMID 39566400, 2024). "Depriving MYC-driven tumors of Trp through a No-Trp diet not only prevents tumor growth but also restores the transcriptional profile of normal liver cells." (PMID 38769298, 2024). "Metabolically, it is well known that MYC overexpression allows cancer cells to become nutrient-independent, inducing a metabolic shift that activates pathways promoting tumor cell survival even in the absence of growth factors or amino acids." (PMID 39596100, 2024). "Conversely, in tumour samples with low NLRP1 expression, there is a notable enrichment of signalling pathways, include E2F targets, G2/M checkpoint, MYC targets version 1, MYC targets version 2 and oxidative phosphorylation." (PMID 39318060, 2024). "Based on these, we propose the hypothesis that M35L mutation possibly exchanges SPOP substrates from oncoproteins (such as GLI2, c-MYC and TRIM24) to tumor suppressors (such as IRF2BP2), therefore reprogramming the tumor properties of SPOP." (PMID 38409107, 2024). "T-cell apoptosis induced by intra-tumor ROS underscores the beneficial effect of glutathione (GSH) in priming T-cell responses and metabolic reprogramming through the activation of mTOR, NFAT, and MYC." (PMID 38891056, 2024). "Knockdown of CDK8 inhibited tumor growth and prolonged the survival of intracranial tumor-bearing mice relative to shNull, reinforcing CDK8 as a crucial factor controlling the growth of MYC-amplified MB." (PMID 39574899, 2024). "The intricate network of TFs, including SOX2, OCT4, NANOG, KLF4, c-MYC,β-catenin, STAT3, NF-κB, HIF-1α and YAP/TAZ, is central to the maintenance of the stem-likeproperties of GSCs, which in turn drive tumor heterogeneity, therapeutic resistance, andrecurrence." (PMID 38716541, 2024).
tumor (continued). "Moreover, the tumor-suppressive effects of DENND2D, which are mediated through MYC pathway regulation and immune cell infiltration, underscores its dual role in cancer control and immune modulation." (PMID 39857609, 2024). "Interestingly, a reciprocal dynamical behaviour was observed with the tumour suppressor PTEN, as well as the apoptosis-mediated pathway and the MYC-mediated apoptosis pathway." (PMID 39179604, 2024). "Combination of MP1 with temsirolimus further significantly suppressed tumor growth by approximately 40% (compared to temsirolimus) and 60% (compared to MP1), suggesting the antitumor combination potential of MP1 with temsirolimus against MYC-driven MB in vivo." (PMID 38200580, 2024). "MYC also affects cell non-autonomous hallmarks including reshaping of the tumour microenvironment, angiogenesis, induction of immunosuppressive cytokine release, and upregulation of immune checkpoint inhibitor proteins." (PMID 38510176, 2024). "Inactivation of MYC by Tet consistently diminished NOX4 induction in P493 cells, confirming that MYC family oncoproteins specifically stimulate NOX4 expression in human tumor cells." (PMID 38493213, 2024). "Strikingly and in contrast to depletion of MYC, a subset of mice shows long-term survival even after doxycycline withdrawal, demonstrating that no tumor cells capable of initiating tumor regrowth remain." (PMID 38365788, 2024). "In contrast, trametinib inhibited IL-6-induced AP-1/JUNB but not MYC transactivation activity in these tumor cells." (PMID 39160158, 2024). "Notably, MYC-dependent cancer cell lines and animal models were found to be significantly more sensitive to genetic or pharmacological SF3B1 inhibition than tumor cells in the normal MYC state." (PMID 39528914, 2024). "Given the significant role of CREPT in transcription regulation and its elevated expression in tumor cells, we hypothesized that CREPT might be involved in the transcriptional activity of MYC in cancer cells." (PMID 39615685, 2024). "Additionally, another MYC-MAX perturbagen, Mycro3 resulted in enhanced CD8+T cell function in surveilling cancer cells and inducing anti-tumor immune response." (PMID 38390324, 2024). "Levels of β-catenin, c-MYC, and CCND1 were negatively correlated with miR-150 overexpression suggesting that miR-150 might decrease CRC growth and operate as a tumor suppressor by blocking β-catenin pathway." (PMID 38632250, 2024). "In addition, pathways related to tumor proliferation (WNT/Beta-Catenin, PI3K/AKT/mTOR, MTORC1, MYC targets V1) and pathway related to DNA mismatch repair (DNA repair) also showed significant negative correlations with miR-24-1-5p expression." (PMID 38840234, 2024). "In MYC‐driven lymphomagenesis, FOXO3 had a remarkable tumour‐suppressor function." (PMID 37987202, 2024). "Also, a MYC-regulated ovarian adenocarcinoma-amplified lncRNA (OVAAL), is reported to promote cell proliferation via a feedback control over MYC stability, thus, targeting OVAAL and MYC simultaneously is expected to produce a stronger tumor suppression effect." (PMID 39075086, 2024). "Despite the reported pro-cancerogenic effects of extra centrosomes, we did not observe any difference in tumor latency in oncogene-driven blood cancer induced by the overexpression of MYC or ABL kinase, when combined with continued Plk4 transgene expression." (PMID 38552015, 2024). "Interestingly, ILCs, particularly ILC3s, in the inflammatory or tumor microenvironment of patients with IBD or CRC expressed significantly higher levels of CTNNB1, and Wnt/β-catenin downstream genes TCF7, VEGFA and MYC, as compared with control tissues." (PMID 38561332, 2024).